E2F1 (E2F transcription factor 1)
Diseases named in the same sentence as E2F1 in open-access papers (continued):
Sharing a sentence is not in itself a finding about the gene and the disease.
neuroblastoma (continued). "Moreover, the expression levels of E2F1 and E2F3 were positively correlated with the risk score in pediatric neuroblastoma patients." (PMID 35764946, 2022). "Moreover, pediatric neuroblastoma patients with age at diagnosis < 18 months and with lower E2F1 expression levels had the best clinical event free survival and overall survival than other sub-groups in TARGET, GSE16476, GSE85047 and E-MTAB-1781 datasets." (PMID 35764946, 2022). "In addition, PCLAF can regulate the expression levels of PTTG1 through E2F1 and promote the proliferation of neuroblastoma cells." (PMID 35210406, 2022). "In the neuroblastoma cell line, the E2F-targeted portions of cancer pathways, thermogenesis, mTOR signaling, insulin signaling, and circadian entrainment were all inhibited, as one would expect based on the previous research on E2F1." (PMID 36271102, 2022). "Moreover, 2179, 5183 and 6143 genes were significantly changed in neuroblastoma patients with higher E2F1 expressions in GSE16476, GSE85047 and E-MTAB-1781 datasets." (PMID 35764946, 2022). "Furthermore, E2F1 and E2F3 were both significantly associated with the overall survival of neuroblastoma in TARGET, GSE16476, GSE85047 and E-MTAB-1781 datasets." (PMID 35764946, 2022). "In addition, in human neuroblastoma tissues, lncNB1, E2F1, or RPL35 RNA expression positively correlates with DEPDC1B RNA expression, and high levels of lncNB1, E2F1, RPL35, or DEPDC1B expression predict poorer patient outcome." (PMID 31690716, 2019). "To address whether there was any potential clinical significance in the levels of PRMT5 and E2F1, we examined gene expression in a collection of 649 human neuroblastoma biopsies taken from early and late (stage 1 to 4) disease and calculated survival probability curves." (PMID 39021294, 2025). "However, the relationships of E2F1 expression and age of diagnosis in neuroblastoma are unclear." (PMID 35764946, 2022). "Also, E2F1 and E2F3 were associated with MYCN amplification and age of neuroblastoma diagnosis." (PMID 35764946, 2022). "We investigated the relevance of PRMT5 and E2F1 in neuroblastoma (NB) and found that elevated expression of PRMT5 and E2F1 occurs in poor prognosis high‐risk disease and correlates with an amplified Myelocytomatosis viral‐related oncogene, neuroblastoma‐derived (MYCN) gene." (PMID 39021294, 2025). "In this respect, it is noteworthy that in clinical neuroblastoma the expression of splicing and RNA processing factor genes was seen to coincide with PRMT5, E2F1 and MYCN levels, and similarly with some of the exon skipping events in the apoptotic genes." (PMID 39021294, 2025). "The mRNA content was determined using several multiplex droplet digital PCR (ddPCR) assays for a neuroblastoma-specific gene panel (PHOX2B, TH, CHRNA3) and a cell cycle regulation panel (E2F1, CDC6, ATAD2, H2AFZ, MCM2, DHFR)." (PMID 37046768, 2023). "For neuroblastoma, it is known that MYCN amplification is a feature of aggressive disease and that this in turn can upregulate E2F1 and MCM2." (PMID 37046768, 2023). "Here, we uncover that CBN attenuated the cell proliferation, invasion, and angiogenesis of neuroblastoma cell lines in a dose-dependent manner via the inhibition of the AKT pathway and the upregulation of miR-34a that targets E2F1." (PMID 35454815, 2022). "In this study, using four neuroblastoma datasets, we showed that, compared with other E2F factors, E2F1 and E2F3 shared similar expressions and prognosis in pediatric neuroblastoma." (PMID 35764946, 2022). "In conclusion, we clarify the existence of the PCLAF/E2F1/PTTG1 axis, which has an imperative role in cell cycle progression in neuroblastoma cells." (PMID 35210406, 2022). "Combinations of E2F1, E2F3 with MYCN amplification or age of diagnosis achieved better prognosis of neuroblastoma." (PMID 35764946, 2022).
neuroblastoma (continued). "Combined the univariable cox regression assay in four independent datasets, E2F1 and E2F3 were most significantly correlated with the event free survival and overall survival of neuroblastoma." (PMID 35764946, 2022). "The expression levels of E2F1 and E2F3 were higher in neuroblastoma patients with MYCN amplification or age at diagnosis ≥ 18 months." (PMID 35764946, 2022). "Based on the expression levels of E2F1 and MYCN amplification, pediatric neuroblastoma patients were divided into four sub-groups." (PMID 35764946, 2022). "Results from both cox regression assay and Kaplan–Meier survival analysis suggested that E2F1 and E2F3 transcription factors were correlated with the event free survival and overall survival of neuroblastoma." (PMID 35764946, 2022). "Combinations of E2F1 expression, E2F3 expression with MYCN amplification or age of diagnosis achieved better prognosis in neuroblastoma." (PMID 35764946, 2022). "Over-expressions of E2F1 or E2F3 were correlated with the shorted event free survival and overall survival of neuroblastoma." (PMID 35764946, 2022). "Expression levels of E2F1 and E2F3 were higher in neuroblastoma patients with MYCN amplification or age at diagnosis ≥ 18 months." (PMID 35764946, 2022). "Combinations of E2F1 expression, E2F3 expression with MYCN amplification or age of diagnosis achieved better prognosis of neuroblastoma." (PMID 35764946, 2022). "Besides, E2F1 could bind to the promoter of BMI1 to initiate its transcription in neuroblastomas." (PMID 33986804, 2021). "Taken together, the data suggest that lncNB1, its binding partner RPL35 and their targets E2F1 and DEPDC1B are required for neuroblastoma cell proliferation and survival." (PMID 31690716, 2019). "In neuroblastoma tumors, SKP2 expression has been shown to tightly correlate with E2F1 expression, and both genes are expressed at significantly higher levels in MYCN amplified tumors." (PMID 23226679, 2012). "In this study we demonstrate that accumulation of reactive oxygen species (ROS) is essential for E2F1 mediated apoptosis in ER-E2F1 PC12 pheochromocytoma, and SH-SY5Y and SK-N-JD neuroblastoma stable cell lines." (PMID 23251571, 2012). "The frequent over‐expression of PRMT5 in diverse human tumours, which includes neuroblastoma, and the critical role ascribed to E2F1 in the cancer cell cycle suggests that PRMT5 and E2F1 may play an important role in driving the malignant phenotype." (PMID 39021294, 2025). "Since E2F1 is a biological target for PRMT5, and because PRMT5 is over‐expressed in neuroblastoma, we reasoned that an important relationship may exist between the two genes that contributes to the aetiology of neuroblastoma." (PMID 39021294, 2025). "We show that CBN profoundly inhibits neuroblastoma cell proliferation, angiogenesis, and invasion in a dose-dependent manner, and induces cell cycle arrest through the inhibition of the AKT pathway and downregulation of miR-34a’s targets CDK2 and E2F1." (PMID 35454815, 2022). "Therefore, functions of E2F1 and E2F3 should be further studied in neuroblastoma cells by using in vivo or in vitro experiments." (PMID 35764946, 2022). "Moreover, the mechanisms of E2F1 and E2F3 in the regulations of metabolism signaling pathways in neuroblastoma should be further studied." (PMID 35764946, 2022). "E2F1 and E2F3 were prognostic factors in all four independent pediatric neuroblastoma cohorts." (PMID 35764946, 2022). "However, additional mechanisms need to be explored, such as the specific mechanism by which PCLAF affects E2F1 expression and how PTTG1 affects neuroblastoma cell cycle progression." (PMID 35210406, 2022). "The abnormal expressions of E2F1 and E2F3 may confer the uncontrolled cell cycle and DNA replication in neuroblastoma." (PMID 35764946, 2022). "E2F transcription factors E2F1 and E2F3 were prognostic makers of neuroblastoma." (PMID 35764946, 2022).
neuroblastoma (continued). "Similarly with E2F1, E2F3 was also additively predicted the clinical overall survival of neuroblastoma with MYCN amplification or age of diagnosis." (PMID 35764946, 2022). "High TRPM2 expression significantly enhanced expression of α1, αv, β1 and β5 integrins in the membrane of neuroblastoma cells and integrin complex formation, through transcriptional mechanisms including increased HIF-1α, E2F1, and FOXM1, resulting in promotion of migration and invasion." (PMID 36446940, 2022). "Furthermore, E2F1 and E2F3 also shared similar downstream transcriptional features in pediatric neuroblastoma." (PMID 35764946, 2022). "The lncRNA lncNB1 directly binds to the ribosomal protein RPL35 and promotes the translation of tumorigenic mRNAs such as E2F1, leading to transcriptional activation of E2F1 target genes such as DEPDC1B, N-Myc protein phosphorylation at serine 62 and stabilization and neuroblastoma tumorigenesis." (PMID 33593347, 2021). "As high levels of lncNB1, RPL35, E2F1, and DEPDC1B expression in tumor tissues correlate with poor prognosis in neuroblastoma patients, our findings identify lncNB1, RPL35, and DEPDC1B as important co-factors for N-Myc-driven oncogenesis and provide therapeutic targets for neuroblastoma." (PMID 31690716, 2019). "Taken together, the data suggest that lncNB1, RPL35, and E2F1 regulate DEPDC1B expression in human neuroblastoma tissues, and that high levels of lncNB1, DEPDC1B, RPL35, and E2F1 expression in tumor tissues predict poor prognosis in neuroblastoma patients." (PMID 31690716, 2019). "Thus, our data demonstrate that lncNB1, its binding protein RPL35 and their target protein E2F1 and target gene DEPDC1B induce neuroblastoma cell proliferation and survival." (PMID 31690716, 2019). "First, we transfected the human neuroblastoma SH-SY5Y cells with 27 mer siRNA duplexes for human E2F1 or trilencer-27 universal scrambled negative control siRNA duplex." (PMID 22848730, 2012). "Over-expression of E2F1 in the neuroblastoma cell line SH-SY5Y induced apoptosis but not in neuroblastoma cell line, SK-N-JD, suggesting that the high activity of E2F1 itself does not cause apoptosis." (PMID 23251571, 2012). "Here, we wanted to elucidate the role that PRMT5, E2F1 and MYCN may take on in neuroblastoma." (PMID 39021294, 2025). "Moreover, E2F1 was a prognostic maker of neuroblastoma independent of MYCN amplification, age of diagnosis and E2F3 expression in TARGET, GSE85047 and E-MTAB-1781 datasets." (PMID 35764946, 2022). "Moreover, the prognostic significance of E2F1 or E2F3 in neuroblastoma was independent of MYCN amplification and age of diagnosis." (PMID 35764946, 2022). "Moreover, E2F1 and E2F3 were independent neuroblastoma prognostic factors." (PMID 35764946, 2022). "Since, E2F1 and E2F3 were prognostic makers of neuroblastoma independent of MYCN amplification and age of diagnosis, the combinations of E2F1 or E2F3 with MYCN amplification or age of diagnosis could achieve better prognostic effects in pediatric neuroblastoma patients." (PMID 35764946, 2022). "In this paper, we highlighted that E2F1 and E2F3 were prognostic makers of neuroblastoma independent of MYCN amplification and age of diagnosis." (PMID 35764946, 2022). "Our results suggested that E2F1 and E2F3 were prognostic makers of neuroblastoma independent of MYCN amplification and age of diagnosis." (PMID 35764946, 2022). "Pediatric neuroblastoma patients without MYCN amplification and with lower E2F1 expression levels had significantly longer event free survival and overall survival in GSE16476, GSE85047 and E-MTAB-1781 datasets." (PMID 35764946, 2022).
neuroblastoma (continued). "E2F3 was also a prognostic maker of neuroblastoma independent of MYCN amplification, age of diagnosis and E2F1 expression in E-MTAB-1781 datasets." (PMID 35764946, 2022). "E2F1 and E2F3 were prognostic factors in neuroblastoma, independent of MYCN amplification and age of diagnosis." (PMID 35764946, 2022). "The E2F1-mediated induction of p19 mRNA and protein was also observed in human cell lines, namely WI-38 fibroblasts, SH-SY5Y neuroblastoma and 293 embryonic kidney cells (data not shown)." (PMID 21765927, 2011).
lung adenocarcinoma (33 papers, 2009 to 2025). A carcinoma that arises from the lung and is characterized by the presence of malignant glandular epithelial cells. "E2F1 is a transcription activator overexpressed in lung adenocarcinoma and squamous cell lung carcinoma tissues, associated with cellular proliferation by counteracting the negative effects of cyclin-cdk inhibitors." (PMID 31867044, 2019). "Although E2F1 overexpression in multiple tumors promotes tumor proliferation, its low expression in lung adenocarcinoma may be associated with promoting immune escape from tumor cells." (PMID 35586682, 2022). "The prognostic HR values of E2F1 in patients with Bladder Urothelial Carcinoma, Colon adenocarcinoma, and Lung adenocarcinoma were 1.10 (P = 0.61), 1.00 (P = 0.99), 1.3 (P = 0.14), respectively." (PMID 37277745, 2023). "In this study, we wanted to identify E2F1-dependent oncogenic lncRNAs so, we transfected A549, an aggressive lung adenocarcinoma cell line, with E2F1 siRNA and evaluated the levels of the six shortlisted lncRNAs." (PMID 35169159, 2022). "In the analyses of oncogenic gene sets, we found six gene sets (SINGH KRAS Dependency Signature, CAMP UP.V1 UP, MYC UP.V1 UP, RB P107 DN.V1 UP, E2F1 UP.V1 UP and CSR LATE UP.V1 UP) associated with lung adenocarcinoma." (PMID 33446784, 2021). "The results showed that the level of DNA methylation was negatively related to the decreased CCNE1 and E2F1 transcription in 370 lung squamous cell carcinoma tissues (p < 0.05) and 456 lung adenocarcinoma tissues (p < 0.05)." (PMID 33613291, 2021). "The transcription levels of E2F1 in lung adenocarcinoma and squamous cell lung carcinoma are higher than those in lung tissues, and their fold changes are 2.142 and 2.084, respectively." (PMID 29754146, 2018). "We found that the expression levels of E2F1/2/3/5/6/7/8 were higher in lung adenocarcinoma and squamous cell lung carcinoma tissues than in lung tissues, whereas the expression level of E2F4 was lower in the former than in the latter." (PMID 29754146, 2018). "Functional connectivity of the top network revealed a strong over-representation of the E2F1 pathway in patients in the F subgroup, suggesting that its activation may be a key genetic determinant associated with the poorer survival of lung adenocarcinoma patients in this subgroup." (PMID 22970185, 2012). "E2F1, a transcription factor that plays a crucial role during S phase progression and apoptosis, triggers apoptosis in various lung adenocarcinoma cell lines by specifically downregulating of c-FLIPS leading to caspase-8 activation at the DISC." (PMID 22348197, 2011). "The specific overexpression of c-FLIPS is also seen in human lung adenocarcinomas with low levels of E2F1." (PMID 22348197, 2011). "Transcriptome data from the TCGA database showed that the RNA level of LRPPRC was positively correlated with that of CDK6 (n = 515, Rho = 0.327, P < 0.0001) and E2F1 (n = 515, Rho = 0.383, P < 0.0001) in lung adenocarcinoma; and the positive correlation tendency was widespread in different tumors." (PMID 37452037, 2023). "Then the correlation analysis of DNA methylation level and transcript level of CCNE1 and E2F1 in 370 lung squamous cell carcinoma and 456 lung adenocarcinoma tissues from TCGA cohort was performed to identify the possible mechanism underlying CCNE1 and E2F1 DNA methylation in NSCLC by cBioPorta." (PMID 33613291, 2021). "Existing data support that E2F1 regulates cell cycle genes that lead to the molecular differences associated with different response to chemotherapies between smoker and non-smoker lung adenocarcinoma." (PMID 24341432, 2013). "E2F1 transcription factor also downregulates c-FLIPS in lung adenocarcinoma." (PMID 25379355, 2013).
lung adenocarcinoma (continued). "While overexpression of the c-FLIPS variant has been reported in human lung adenocarcinomas with low levels of E2F1, c-FLIPL protein expression was not altered." (PMID 25379355, 2013). "The combination of a peptide targeting transcription of E2F-1, 2, and 3a, with cisplatin, and especially with pemetrexed, showed enhanced antitumor activity in-vitro and in-vivo and has promise for the treatment of patients with various tumors, and in particular, lung adenocarcinoma." (PMID 33652640, 2021). "Expression of E2F1’s well-known downstream target genes was significantly upregulated in subgroup F, indicating that E2F1 was highly activated in subgroup F and that E2F1-mediated regulation of EZH2 may be a key genetic event associated with poor prognosis in lung adenocarcinoma." (PMID 22970185, 2012). "The results revealed that MYBL2, CENPA, FOXM1, E2F1, ZNF367, and HMGA1 are the most relevant upstream transcription factors in lung adenocarcinoma." (PMID 40885709, 2025). "Subsequent survival analyses confirmed that overexpression of MYBL2 outperformed both E2F1 and FOXM1 transcription factors in identifying lung adenocarcinoma patients with poor outcomes." (PMID 33489883, 2020). "To investigate SCL/TAL 1 interrupting locus (STIL)’s role and prognostic significance in lung adenocarcinoma (LUAD) progression, we examined STIL and E2 promoter binding factor 1 (E2F1) expression and their impacts on LUAD prognosis using Gene Expression Profiling Interactive Analysis (GEPIA)." (PMID 39735672, 2025). "For identifying E2F1-dependent oncogenic long non-coding RNAs (lncRNAs), we carried out genome-wide transcriptome analysis and discovered an lncRNA, EMSLR, which is induced both in lung adenocarcinoma (LUAD) and lung squamous cell carcinoma (LUSC)." (PMID 35169159, 2022). "In lung adenocarcinoma, E2F1 is downregulated by ATO leading to increased activation of caspase 3 and Bid, and downstream disruption of the cell cycle stages G1 to S phases which are modulated by E2F transcription factor 1 (E2F1)." (PMID 36145693, 2022). "The results indicated that the expression levels of E2F1, E2F2, E2F3, E2F5, E2F6, E2F7, and E2F8 were higher in lung adenocarcinoma and squamous cell lung carcinoma tissues than in lung tissues, whereas and the expression level of E2F4 was lower in the former than in the latter." (PMID 29754146, 2018). "The formation of the enlarged LAMP2 particles due to E2F1 depletion was also found in human lung adenocarcinoma cell line A549, suggesting that such phenomenon is not cell type-specific." (PMID 26356814, 2015). "A differentially regulated gene module identified by nDGE, which is enriched for cell cycle genes and E2F1 targeted genes, plays a role attributing to the differences between smoker and non-smoker lung adenocarcinoma." (PMID 24341432, 2013). "nDGE results suggest that a differentially regulated gene module, which is enriched for cell cycle related genes and E2F1 targeted genes, plays a role in the molecular differences between smoker and non-smoker lung adenocarcinoma." (PMID 24341432, 2013). "The analyses suggest that E2F1 might regulate cell cycle related genes in smoker and non-smoker samples and play a role contributing to the molecular differences between smoker and non-smoker lung adenocarcinoma." (PMID 24341432, 2013). "Complex effects on rRNA transcription, both positive and negative, have been ascribed to E2F1, E2F4, and E2F6, when studied in transfected human lung adenocarcinoma H358 cells." (PMID 19838300, 2009).